KMT2E (lysine methyltransferase 2E (inactive))
Description:
Associates with chromatin regions downstream of transcriptional start sites of active genes and thus regulates gene transcription. Chromatin interaction is mediated via the binding to tri-methylated histone H3 at 'Lys-4' (H3K4me3). Key regulator of hematopoiesis involved in terminal myeloid differentiation and in the regulation of hematopoietic stem cell (HSCs) self-renewal by a mechanism that involves DNA methylation (By similarity). Also acts as an important cell cycle regulator, participating in cell cycle regulatory network machinery at multiple cell cycle stages including G1/S transition, S phase progression and mitotic entry. Recruited to E2F1 responsive promoters by HCFC1 where it stimulates tri-methylation of histone H3 at 'Lys-4' and transcriptional activation and thereby facilitates G1 to S phase transition. During myoblast differentiation, required to suppress inappropriate expression of S-phase-promoting genes and maintain expression of determination genes in quiescent cells (By similarity). [Isoform NKp44L]: Cellular ligand for NCR2/NKp44, may play a role as a danger signal in cytotoxicity and NK-cell-mediated innate immunity.
Synonyms: MLL5; HDCMC04P; SETD5B; NKp44L; ODLURO
Tractability: Antibody: UniProt places it where antibodies can reach, with high confidence; its Gene Ontology location is reachable by antibodies, with medium confidence. PROTAC: UniProt records ubiquitination sites on it; ubiquitination databases record sites on it; its protein half-life has been measured.
Target class: Writer; Protein methyltransferase; Epigenetic regulator
Gene: Protein-coding gene on chromosome 7 (104,940,943 to 105,115,019, forward strand). Ensembl gene ENSG00000005483.
Subcellular location: Chromosome; Cytoplasm, cytoskeleton, microtubule organizing center, centrosome; Nucleus speckle; Nucleus, nucleoplasm (Isoform 3); Cytoplasm (Isoform NKp44L); Cell membrane
Subcellular location (Human Protein Atlas): Nucleoplasm; Cytosol; Nuclear bodies
Gene Ontology:
Molecular function: enzyme binding; histone H3 methyltransferase activity; histone H3K4me3 reader activity; protein binding; transcription coactivator activity
Biological process: positive regulation of DNA-templated transcription; positive regulation of G1/S transition of mitotic cell cycle; epigenetic regulation of gene expression; erythrocyte differentiation; neutrophil activation; neutrophil mediated immunity; regulation of DNA-templated transcription; chromatin organization; regulation of gene expression
Cellular component: chromatin; chromosome; cytoplasm; cytosol; euchromatin; nuclear speck; nucleoplasm; nucleus; plasma membrane; protein-containing complex; Rpd3L-Expanded complex; Set3 complex; centrosome
Genetic constraint (gnomAD): Loss-of-function variants: 21 observed, 139.38 expected, observed/expected ratio (o/e) 0.15, 90% interval 0.11 to 0.22. The upper end of that interval is the gene's LOEUF score, 0.22, which puts it in group 1 of 6, group 1 being the genes least tolerant of losing a copy. Missense variants: 1,829 observed, 2,006 expected, observed/expected ratio (o/e) 0.91, 90% interval 0.88 to 0.95. Synonymous variants: 724 observed, 717.55 expected, observed/expected ratio (o/e) 1.01, 90% interval 0.95 to 1.07.
Gene-disease validity (ClinGen):
ClinGen rates the evidence that KMT2E causes each of these diseases.
complex neurodevelopmental disorder (autosomal dominant): Definitive. A disorder that involves more than one phenotype associated with the central nervous system, including but not limited to intellectual disability, autism, and seizures (epilepsy).
Homologues: Orthologues: chimpanzee KMT2E (99% identical), macaque KMT2E (99% identical), pig KMT2E (94% identical), dog KMT2E (93% identical), mouse Kmt2e (90% identical), rat Kmt2e (89% identical), rabbit KMT2E (72% identical), tropical clawed frog kmt2e (67% identical), zebrafish kmt2e (39% identical), Drosophila melanogaster upSET (22% identical), Caenorhabditis elegans set-26 (13% identical), Caenorhabditis elegans set-9 (13% identical), and 1 more. Paralogues in human: SETD5 (26% identical).
Diseases named in the same sentence as KMT2E in open-access papers:
KMT2E is named in the same sentence as 39 diseases in open-access papers, as found by Europe PMC text mining. Sharing a sentence is not in itself a finding about the gene and the disease. The quoted sentences say what the papers report.
epilepsy (3 papers, 2022 to 2023). A brain disorder characterized by episodes of abnormally increased neuronal discharge resulting in transient episodes of sensory or motor neurological dysfunction, or psychic dysfunction. "Heterozygous Inactive Lysine Methyltransferase 2E (KMT2E) variants result in a spectrum of neurodevelopmental disorders, epilepsy, and functional GI disturbances." (PMID 35874825, 2022). "Additionally, there are also variants in genes related to epilepsy, such as CACNA1D (AUT142), CHD1 (AUT183), KMT2E (AUT184), and CHD2 (AUT195)." (PMID 38003033, 2023).
myeloid malignancies (3 papers, 2012 to 2023). "For example, we observed a H3K4me3 peak decrease at the tumor suppressor gene KMT2E that is frequently deleted in myeloid malignancies; the product of this gene controls cell cycle and genomic stability and regulates hematopoiesis." (PMID 33837044, 2021). "Other histone methylating genes, such as KMT5B/EZH1/KMT2D/KMT2E/SETD5, were also included in brown module, and related to pathological process or prognosis of myeloid neoplasms (MDS/AML)." (PMID 37953918, 2023).
COVID-19 (2 papers, 2021 to 2022). A disease caused by infection with severe acute respiratory syndrome coronavirus 2. "KMT2E is a gene related to lysine degradation in mono-CD14+ cells and has been shown to be downregulated in severe COVID-19 patients." (PMID 35755819, 2022). "In module 1, NSD1, KMT2E, and SETD2, which are histone lysine methyltransferases involved in cell development and differentiation, were expressed at lower levels in COVID-19 patients." (PMID 33936072, 2021). "In mono-CD16+ cells in COVID-19 patients, we found reduced lysine degradation (downregulation of NSD1, KMT2E, and SETD2) and enhanced OXPHOS, which may inhibit M2 macrophage polarization and differentiation through the cAMP and MAPK signaling pathways or the PI3K, AKT and mTOR signaling pathways." (PMID 33936072, 2021). "The mono-CD16+ cell population in COVID-19 patients showed reduced transcription levels of genes related to lysine degradation (NSD1, KMT2E, and SETD2) and elevated transcription levels of genes involved in OXPHOS (ATP6V1B2, ATP5A1, ATP5E, and ATP5B), which may inhibit M2-like polarization." (PMID 33936072, 2021).
infertile (2 papers, 2011 to 2020). "Besides, KMT2E, termed as MLL5, had been demonstrated to be required for normal spermatogenesis, its knockout mouse showed a post meiotic phenotype and infertile." (PMID 32273886, 2020).
leukemia (2 papers, 2013 to 2023). A malignant (clonal) hematologic disorder, involving hematopoietic stem cells and characterized by the presence of primitive or atypical myeloid or lymphoid cells in the bone marrow and the blood. "Previously, the role of KMT2E expression has been implicated in the prognosis of leukemias." (PMID 37583580, 2023).
autism spectrum disorder (1 paper, 2019). A spectrum of developmental disorders that includes autism, and Asperger syndrome. "However, an exome sequencing study reported that KMT2E is strongly associated with autism spectrum disorder." (PMID 31639064, 2019).
gastric cancer (1 paper, 2022). A primary or metastatic malignant neoplasm involving the stomach. "Conversely, in five of these genes, all clonally mutated patients had mutations that were likely pathogenic (CTNNB1, ELF3, ATM, KMT2E, and PIK3CA), lending stronger support to their candidate gastric cancer driver status." (PMID 36970058, 2022).
tumor (27 papers, 2007 to 2025). "Although the DEK gene is related to tumor processes in humans, it is involved in stages of cell differentiation, and complementarity to the KMT2E gene, which acts on cell proliferation, allows us to reinforce the possibility that ALA-L animals are less precocious." (PMID 35629975, 2022). "However, a slew of evidence suggests that KMT2E may be involved in cancer tumor inhibition in certain kinds of subtypes." (PMID 35058979, 2022). "The mutations in this tumor included 3 predicted high impact mutations in MTOR a regulator of stress response, OGT a glycosyltransferase that modifies a broad range of targets including H2B, AKT1, EZH2, PFKL, KMT2E/MLL5, MAPT/TAU and HCFC1, and FAM129B a negative regulator of apoptosis." (PMID 28415633, 2017). "High levels of KMT2A, KMT2C, KMT2E, and KMT2H were shown to be strongly connected with types 3 and 5 infiltrations (C3 and C5), indicating that greater gene expression is linked to a healthy immune system and that these genes may play an important function in tumor suppression." (PMID 35058979, 2022). "In addition, we identified mutations in epigenetic regulation genes, such as KMT2D, KMT2E, SMYD3, ASH1L, KMT2C, and KMD4B, in the tumor clones." (PMID 38010945, 2024).
cancer (11 papers, 2012 to 2024). A tumor composed of atypical neoplastic, often pleomorphic cells that invade other tissues. "KMT2E, for example, has been linked to greater cell resistance to fluorouracil (a medication used to treat malignancies of the stomach, colon, esophagus, rectal, and liver), while KMT2G has been linked to enhanced cell sensitivity to the same drug." (PMID 35058979, 2022). "The greatest expression of KMT2E was found in all cancer cell lines, whereas the lowest expression was found in KMT2B." (PMID 35058979, 2022). "ATP1A1, KMT2E and WASF2 were known as the hallmarker of cancers and overexpression of these genes promote the survival of cancer cells, while RAD23A acts as a negative regulator of anti-virus response and might correlate directly with the HPV infection." (PMID 36420261, 2022).
neurodevelopmental disorder (2 papers, 2021 to 2022). A behavioral and cognitive disorder with onset during the developmental period that involves impaired or aberrant development of intellectual, motor, or social functions. "De novo mutations in KMT2E cause a spectrum of neurodevelopmental disorders including ASD." (PMID 34493297, 2021).
KMT2E also shares sentences with these, for which no sentence is quoted: viral infection (4 papers); HIV-1 infection (3); infection (3); acute myeloid leukemia (2); cervical cancer (2); glioblastoma (2); acute promyelocyte leukemia (1); AIDS (1); astroblastoma (1); atherosclerosis (1); autism (1); breast carcinoma (1); breast tumours (1); cardiomyopathy (1); cervical adenocarcinoma (1); cervical squamous cell carcinoma (1); chromophobe carcinoma (1); clear cell carcinoma (1); colon cancer (1); HCMV infection (1); immune dysfunction (1); influenza (1); liver fibrosis (1); Macrocephaly (1); male infertility (1); O'Donnell-Luria-Rodan syndrome (1); papillary carcinoma (1); renal carcinoma (1); ZIKV infection (1).